MMP9 (matrix metallopeptidase 9)
Diseases named in the same sentence as MMP9 in open-access papers (continued):
Sharing a sentence is not in itself a finding about the gene and the disease.
aortic atherosclerosis (2 papers, 2020 to 2023). A atherosclerosis that involves the aorta. "This is consistent with our recent report that MF-specific IGF-1 overexpression downregulates MMP9 in peritoneal MFs and decreases aortic atherosclerosis in Apoe–/– mice." (PMID 36602878, 2023). "In the present study, we investigated the time course of ETAR expression in high-fat diet-induced aortic atherosclerosis in ApoE−/− mice and in human advanced atherosclerotic plaques in correlation to smooth muscle actin (SMA) and matrix metalloproteinase 9 (MMP-9)." (PMID 33255872, 2020).
aortic insufficiency (2 papers, 2020). "However, MMP1 rs1799750 and MMP9 rs3918242 seem to be associated with the degree of aortic regurgitation in these patients." (PMID 33029260, 2020). "However, rs1799750 MMP1 and rs3918242 MMP9 seem to be associated with the degree of aortic regurgitation." (PMID 33029260, 2020). "However, we have shown that the MMP1 and MMP9 genes may partially contribute to the incidence of aortic regurgitation." (PMID 33029260, 2020).
aortic valve disease (2 papers, 2012 to 2019). "For example, doxycycline, described as DILE inducer, has been used as MMP-9 inhibitor in lung injury and aortic valve disease induced by cardiopulmonary bypass." (PMID 30967870, 2019). "The BAV group with a combination of aortic valve diseases had significantly increased MMP-8 and MMP-9 levels in the convex aortic sites." (PMID 22645456, 2012).
appendicitis (2 papers, 2023). Acute inflammation of the vermiform appendix. "However, Swedish authors have reported that among new inflammatory markers, serum amyloid A (SAA), matrix metalloproteinase (MMP-9), and myeloperoxidase (MPO) were the strongest discriminators of all cases of appendicitis." (PMID 37509519, 2023).
arterial disorder (2 papers, 2016 to 2024). An impairment of the structure or function of the blood vessels which carry blood away from the heart. "Thus MMP-9 has been implicated in a host of human arterial disorders." (PMID 27075045, 2016). "Intimal, medial, and wall thickening of IgAN arteriopathy are associated with VEGF, MMP-9, PCNA, and ERK1/2." (PMID 39669374, 2024). "VEGF (0.35 ± 0.90), MMP-9 (0.38 ± 0.12), PCNA (0.43 ± 0.12), ERK1/2 (0.31 ± 0.11), and NF-κB (0.37 ± 0.14) were the highest in IgAN with arteriopathy group." (PMID 39669374, 2024).
Arterial thrombosis (2 papers, 2021 to 2025). The formation of a blood clot inside an artery. "Among the polymorphisms analyzed, a statistically significant association was identified between the MMP-9 rs3918242 CT genotype and an increased risk of arterial thrombosis (OR = 4.206, CI 1.337–13.234, p = 0.014)." (PMID 40724896, 2025). "Specifically, the MMP-9 rs3918242 CT genotype (compared to CC) was significantly associated with an increased risk of arterial thrombosis (OR = 4.206, CI 1.337–13.234, p = 0.014) and overall thrombotic events (both arterial and venous thromboses combined) (OR = 3.200, CI 1.110–9.258, p = 0.031)." (PMID 40724896, 2025). "Additionally, the MMP-9 rs3918242 variant showed a significant association with both arterial thrombosis and overall thrombotic events (arterial and venous combined; p < 0.05)." (PMID 40724896, 2025).
Ascites (2 papers, 2021 to 2025). Accumulation of fluid in the peritoneal cavity (between the layers of the peritoneum that lines the abdomen). "Some studies suggest that interplay between VEGF and MMP-2 contributes to ascites accumulation, while others highlight the role of VEGF and MMP-9 in this process." (PMID 41009634, 2025).
autoimmune encephalitis (2 papers, 2017 to 2022). Inflammation of the brain secondary to an immune response triggered by the body itself. "MMP-9 upregulation occurs in inflammatory demyelinating diseases in the CNS, and its production has been associated with blood–brain barrier damage in an experimental autoimmune encephalitis model." (PMID 35566760, 2022). "MMP9-mediated breakdown of the basal lamina and destruction of gap junctions in the neurovascular unit result in increased CNS permeability and inflammation in autoimmune encephalitis, hypoxic brain injury, and other diseases." (PMID 28086917, 2017).
bacterial pneumonia (2 papers, 2022 to 2025). Acute infection of the lung parenchyma caused by bacteria (e.g., Streptococcus pneumoniae, Haemophilus influenzae, Chlamydia pneumoniae, Mycoplasma pneumoniae, and Legionella pneumophila). "The CCL18, CXCL9, CXCL10, CXCL11, and MMP9 levels were also elevated in patients with other respiratory diseases, such as bacterial pneumonia and COPD." (PMID 40269953, 2025). "The balance of MMP-9/TIMP-1 and the activity of MMP-9 appear to play important roles in the pathology of bacterial pneumonia." (PMID 36142454, 2022).
bowel cancer (2 papers, 2006 to 2022). "Increased levels of an enzyme called matrix metalloproteinase 9 (MMP-9) have been found to be associated with bowel cancer and conditions that may lead to bowel cancer, and this can be measured from a blood sample." (PMID 17059590, 2006). "If this were the case, measurement of MMP-9 levels could be used by general practitioners to assist in the identification of people who were most likely to have bowel cancer or conditions that may lead to bowel cancer, and who should, therefore, be referred most urgently to secondary care." (PMID 17059590, 2006).
bruxism (2 papers, 2020 to 2025). Excessive clenching of the jaw and grinding of the teeth. "In adults, there was an association between bruxism and MMP9 (rs13925, p = 0.0001) and bruxism and COMT (rs6269, p = 0.003) in genotype evaluation." (PMID 32471213, 2020). "MMP9 is implicated in a number of neurodegenerative disorders and is associated with stress conditions, which is possibly associated with bruxism." (PMID 32471213, 2020). "In addition, in adults, there was an association between bruxism and MMP9 (rs13925, p = 0.0001) and bruxism and COMT (rs6269, p = 0.003)." (PMID 32471213, 2020). "In aggregate, the evidence from mice that MMP9 expression changes under stress and our results showing that the gene associates with bruxism provide support to the idea that MMP9 genetic variants may predispose individuals, once exposed to stressful conditions, to clench or grind their teeth." (PMID 32471213, 2020). "Variations in genes like 5HTR2A, DRD2, DRD3, ANKK1, COMT, MMP9, ACTN3, and ANKK1 are linked with the susceptibility to Bruxism." (PMID 40291793, 2025). "Our hypothesis was that MMP2, MMP9, and/or COMT associate with bruxism, and that variation in these genes may be biomarkers of the risk of developing the condition." (PMID 32471213, 2020). "In summary, we have provided statistical evidence for the role of MMP9 in self-reported bruxism in adults and suggest that bruxism is the result of stress and could be detected early if surrogates of stress are evaluated." (PMID 32471213, 2020).
Burkitt lymphoma (2 papers, 2008 to 2017). A rare form of malignant mature B-cell non-Hodgkin lymphoma. "In previous studies, it has been reported that PEG10 could induce migration of Burkitt’s lymphoma cells via upregulation of MMP-2 and MMP-9." (PMID 28193232, 2017).
calcification (2 papers, 2021 to 2025). Process by which organic tissue becomes hardened by the physiologic deposit of calcium salts. "OPN can promote inflammation and participate in the activation of arterial calcification in Ang II mice, increasing the activity of Matrix metalloproteinase-9 (MMP-9)." (PMID 34901023, 2021). "The upregulation of SOST effectively downregulates the expression of matrix metalloproteinase 9 (MMP9) and OPG, which are involved in the activation of arterial calcification in Ang II mice." (PMID 40563496, 2025).
Chagas cardiomyopathy (2 papers, 2017 to 2021). A disease of the cardiac muscle developed subsequent to the initial protozoan infection by trypanosoma cruzi. "Among MMPs, the gelatinases MMP-2 and MMP-9 have been associated with cardiovascular disorders, including Chagas' cardiomyopathy." (PMID 28118356, 2017). "Medeiros NI, Gomes JAS, Correa-Oliveira R. Synergic and antagonistic relationship between MMP-2 and MMP-9 with fibrosis and inflammation in Chagas’ cardiomyopathy." (PMID 34644785, 2021). "MMP-2 appears to be related to cardiac-protective and regulatory functions in IND group, while predominance of MMP-9 can be identified as an inflammatory booster, favoring the development of Chagas cardiomyopathy." (PMID 28118356, 2017). "Whereas MMP-2 seems to be involved in regulation of the immune response, MMP-9 appears to be related to inflammation and development of Chagas cardiomyopathy." (PMID 28118356, 2017).
childhood asthma (2 papers, 2010 to 2024). "In the present study we investigated whether genetic variations in MMP-9 influence the development of different forms of childhood asthma." (PMID 20181264, 2010).
chronic hepatitis (2 papers, 2011 to 2022). An active inflammatory process affecting the liver for more than six months. "Moreover, serum MMP-9 levels decrease as chronic hepatitis progresses to cirrhosis, while TIMP-1 levels increase along with an increase of the degree of fibrosis (r = 0.73, P < 0.001)." (PMID 21849046, 2011).
chronic venous insufficiency (2 papers, 2014 to 2022). Chronic form of venous insufficiency (disease). "In the skin of patients affected by severe chronic venous insufficiency (CVI), an elevated gene expression for MMP-1, MMP-2, MMP-9, and MMP-13 has been demonstrated." (PMID 35456498, 2022). "In a follow-up study of rat chronic venous insufficiency segments exposed to increased tension, the same group demonstrated increased MMP-2 and MMP-9, and reduced contractility of the vein segment." (PMID 25520775, 2014). "Multiple studies have confirmed increased levels of tissue and plasma MMPs in chronic venous insufficiency, including MMP-1, MMP-2, MMP-3, MMP-9, and MMP-13." (PMID 25520775, 2014).
cleft lip (2 papers, 2021 to 2023). Congenital defect in the upper lip where the maxillary prominence fails to merge with the merged medial nasal prominences. "This human palate study suggests that MMP-9 and its inhibitors are the main regulatory proteins of extracellular matrix (ECM) expression in unilateral cleft lip and/or palate development." (PMID 33672637, 2021).
colon adenoma (2 papers, 2007 to 2020). An adenoma that arises from the colon. "Additionally, LCN2 acts as a subunit of the MMP-9 that has been observed in increased levels in tumor cells in the transition from colonic adenomas to carcinomas." (PMID 17201907, 2007).
colorectal adenocarcinoma (2 papers, 2014 to 2020). The most common type of colorectal carcinoma. "High expressions of Id1 and matrix metalloproteinase 9 (MMP9) have tight correlations with the development and progression of colorectal adenocarcinoma and have positive correlations with microvascular density." (PMID 32410828, 2020).
colorectal tubulovillous adenoma (2 papers, 2012 to 2021). A neoplasm that arises from the glandular epithelium of the colonic and rectal mucosa. "The levels of 20S proteasomes in exosomes, MMP9+, MMP9+/MMP2+/EMMPRIN+ in CD9-positive blood plasma exosomes are associated with the risk of malignant transformation of colorectal tubulovillous adenomas." (PMID 33773551, 2021).
concussion (2 papers, 2016 to 2019). A concussion, also known as a mild traumatic brain injury (mTBI), is a head injury that temporarily affects brain functioning. "Recently identified blood biomarkers for the diagnosis of concussion, such as matrix metalloproteinase 9 (MMP9) and galectin 3, whose synthesis is upregulated in response to injury, may represent potential targets for therapeutic intervention in mTBI." (PMID 28030563, 2016).
Convulsive status epilepticus (2 papers, 2011 to 2012). A type of status epilepticus characterized by a prolonged bilateral tonic-clonic seizure, or repeated bilateral tonic-clonic seizures without recovery between. "In epileptogenesis, serum MMP-9 levels and the ratio of MMP-9 to tissue inhibitor of metalloproteinase-1 are elevated in children with various febrile seizures and convulsive status epilepticus." (PMID 22567285, 2012). "Serum MMP-9 levels and the ratio of MMP-9 to TIMP-1 are elevated in children with various febrile seizures and convulsive status epilepticus." (PMID 22235372, 2011).
cutaneous leishmaniasis (2 papers, 2014 to 2023). Leishmaniasis affecting the skin. "A study showed an increase in MMP-9 release by cells from individuals with cutaneous leishmaniasis compared to healthy individuals." (PMID 37587436, 2023). "The MMP-9 production by CL patients was presented in higher levels when compared with healthy subjects and early cutaneous leishmaniasis (ECL) patients, and the levels of MMP-9 inhibitor, TIMP-1, were lower in CL patients when compared to healthy subjects." (PMID 25393535, 2014).
cystic kidneys (2 papers, 2020 to 2023). "To explore new functions for MMP9 in kidney cysts formation and disease progression, we generated a mouse model by breeding juvenile cystic kidney (jck) mice with MMP9 deficient mice." (PMID 38039285, 2023). "To specify the role of MMP9 in cystic disease, we bred jck (juvenile cystic kidneys) mice with MMP9 deficient mice." (PMID 38039285, 2023). "Knowing that periostin protein level is increased in MMP9 deficient kidney compared to control cystic kidney, we next aimed to understand whether the accumulation of this protein contributes to the severity of the kidney disease observed in mice lacking MMP9." (PMID 38039285, 2023). "MMP9 enzymatic activity monitored by zymography phenocopied the increase of MMP9 protein level in jck kidney and scanning of the zymograms showed a 6.8-fold increase of MMP9 enzymatic activity in jck cystic kidneys compared to controls." (PMID 38039285, 2023). "We next investigated the location of periostin and MMP9 in control cystic kidney." (PMID 38039285, 2023). "Decreased renal function in jck-MMP9-/- was due to the greater severity of renal lesions observed on histological sections as shown by an increase of the number of cysts and of the percentage of cystic kidney tissue in jck-MMP9 -/- compared to jck-MMP9+/+ mice." (PMID 38039285, 2023).
demyelination (2 papers, 2022 to 2025). "After ischemic insult, OPCs secrete matrix metalloproteinase-9 (MMP9) at sites where blood-brain barrier permeability was observed, before demyelination occurred." (PMID 35741083, 2022).
diverticulosis (2 papers, 2023 to 2025). "Allele T of MMP9 rs3918242 was more prevalent in patients with diverticulosis (p < 0.03)." (PMID 38004080, 2023). "The genes regulating ECM turnover, including TIMP1, MMP3, and MMP9, are involved in diverticulosis development." (PMID 40428403, 2025). "The genotype distribution of MMP9 rs3918242 differed significantly between patients with diverticulosis and controls, with a higher frequency of the CT genotype and a lower frequency of the CC genotype." (PMID 38004080, 2023). "Private haplotypes in individuals with diverticulosis included MMP3 −1715 5A/5A|MMP9 −1562 C/T|MMP12 −82 G/G (2%) and MMP3 −1715 6A/6A|MMP9 −1562 C/T|MMP12 −82 A/G (2%)." (PMID 38004080, 2023). "Additionally, an increased frequency of the MMP9 −1562 T allele manifested in patients with diverticulosis as opposed to their healthy counterparts." (PMID 38004080, 2023). "Among patients with diverticulosis, the most prevalent haplotypes included MMP3 −1715 5A/5A|MMP9 −1562 C/C|MMP12 −82 A/A (31%) and MMP3 −1715 5A/6A|MMP9 −1562 C/T|MMP12 −82 A/G (14%)." (PMID 38004080, 2023).
Down syndrome (2 papers, 2018 to 2023). "It has been reported that MMP-9 shows higher activity or amount in comparison with controls in many different brain conditions, including autism and Down syndrome." (PMID 29342922, 2018). "In this review, we describe mechanisms of proteolytic enzymes (MMP-9 and plasminogen activation system), their role in Down syndrome, their inhibition by EGCG, possible degradation of this polyphenol and the ability of EGCG and its degradation products to cross the blood–brain barrier." (PMID 29342922, 2018). "In Down syndrome, the availability of mature NGF is compromised by diminished tPA/plasminogen → plasmin activity, which limits the production of NGF, further lowered by the increased activity of MMP-9 that degrades NGF." (PMID 29342922, 2018).
dyslipidaemia (2 papers, 2021). "Carvedilol and alendronate exerted a bone preservative role and attenuated dyslipidaemia and inflammation in accordance with their respective effect on MMP-9." (PMID 34610044, 2021).
dystrophinopathy (2 papers, 2020 to 2022). "Reports suggested the involvement of MMP-9 in dystrophinopathy, and MMP-9 inhibition has beneficial effects in terms of reduced fibrosis, macrophage infiltration, and decreased necrosis." (PMID 36289739, 2022).
endometrial endometrioid carcinoma (2 papers, 2019 to 2023). "Between the subgroups of malignant endometrium, only endometrial serous carcinoma showed a significant difference from grade 1 endometrioid endometrial carcinoma with its higher immunoreactivity with MMP-9 (p < 0.05)." (PMID 36945954, 2023). "Nonstaining with MMP-9 was highest in the atrophic endometrium (80%), which significantly differed from the serous and all grades of endometrioid endometrial carcinomas (0%) (p < 0.05)." (PMID 36945954, 2023).
endophthalmitis (2 papers, 2025). An infectious process affecting the internal structures of the eye. "The observation that NGAL and MMP-9 were correlated in both endophthalmitis and control vitreous is consistent with previous reports that these cytokines form heterodimers." (PMID 40563988, 2025). "We also reported impaired blood-retinal barriers during endophthalmitis; thus, targeting MMP-9 may help preserve retinal integrity and mitigate disease." (PMID 40512033, 2025). "In the HVIP1 vitreous, there were a number of significant correlations identified: CRP/Myoglobin, IGFBP-4/SAA, IGFBP-4/VCAM-1, and VCAM-1/SAA in the endophthalmitis group; MPO/NGAL, CRP/SAA, and Cystatin C/Myoglobin in controls; and NGAL/MMP-9 in both groups." (PMID 40563988, 2025). "In the patient sera, MMP-9, MPO, Calprotectin, NGAL, SAA (HVIP1), and MCP-1 (HIP1) were all significantly elevated in endophthalmitis samples, which was unexpected as pathology was thought to be localised with minimal systemic effects." (PMID 40563988, 2025).
ependymoma (2 papers, 2000 to 2019). A WHO grade II, slow growing tumor of children and young adults, usually located intraventricularly. "With ependymoma tissue models, higher (2–4 fold) MMP-9 release was observed in cultures containing fetal ECM, while TIMPs were detected at much lower levels overall (0.3–0.5 fold) compared to other ECM types." (PMID 31586101, 2019).
epidermolysis bullosa (2 papers, 2022 to 2024). Epidermolysis bullosa (EB) is a group of genetic skin diseases that cause the skin to blister very easily. "MMP9 is also associated with ECM remodeling after wound closure and its overexpression is associated with chronic wounds and other skin disorders such as epidermolysis bullosa or cicatricial pemphigoid." (PMID 39408993, 2024).
epithelial dysplasia (2 papers, 2017 to 2021). "Evidence also indicates that VEGFR-2 and MMP-9 protein levels are associated with epithelial dysplasia grading." (PMID 29113419, 2017). "Compared with the blank control group, injection of CAL27/MMP-9/shRNA or SCC15/MMP-9/shRNA cells led to mild to moderate epithelial dysplasia in the mouse tongue mucosa." (PMID 33828938, 2021). "Previous studies suggested that Col IV continuity was destroyed and MMP-9 positive cells were increasing in the zone adjacent to fragmented basement membranes in epithelial dysplasia and cancer." (PMID 29113419, 2017).